CD68 (CD68 molecule)
Diseases named in the same sentence as CD68 in open-access papers (continued):
Sharing a sentence is not in itself a finding about the gene and the disease.
meningioma (24 papers, 2013 to 2026). A generally slow growing tumor attached to the dura mater. "In a subsequent study, Han and colleagues analyzed PD-L1 expression together with CD68 expression (a macrophage marker) in a cohort of 96 meningioma specimens (n = 16 WHO°1, n = 62 WHO°2 and n = 18 WHO°3) using IHC/TMA." (PMID 39273576, 2024). "For example, a high degree of macrophage infiltration (CD68 + macrophages and CD68 + CD163 + M2 macrophages) has been associated with tumour aggressiveness and therapy resistance of meningiomas." (PMID 38102708, 2023). "To identify the infiltration and functional characteristics of macrophages in meningiomas and adjacent normal meningeal tissue, we performed IHC staining and analyzed the expression of CD68, CD163, and CD206." (PMID 35637794, 2022). "In the present investigation, we found that spinal meningiomas have a significantly lower density of CD68+ macrophage infiltrates." (PMID 35205781, 2022). "Diffuse CD68+ macrophage infiltrates were observed in 31.25% of the primary meningiomas, whereas 57.1% of the recurrent meningioma tissues included diffuse CD68+ macrophage infiltrates." (PMID 35453901, 2022). "In the present series we observed a trend that PC meningiomas exhibiting an increased MIB-1 index are overlapped by the simultaneous presence of dense CD68+ macrophage infiltrates." (PMID 35877258, 2022). "Diffuse CD68+ staining was observed in 44 (50.0%) of the spinal meningiomas, whereas in the cranial meningioma group 208 patients had diffuse CD68+ macrophage infiltrates, respectively (Pearson ́s chi-squared test (two-sided): p = 0.001)." (PMID 35205781, 2022). "The results confirmed that an increased percentage of CD68−/PD-L1+ tumor cells correlated with WHO grade using a tumor microarray of 96 meningiomas." (PMID 33611710, 2021). "Most infiltrating immune cells in meningiomas have a phenotype consistent with an HLA-DR+ CD14+ CD68+ CD16−/+ CD33−/+ monocyte/macrophage lineage origin." (PMID 29584702, 2018). "CD68+ cells are present in meningiomas even if to a lesser extent than in GBM, but their potential role in growth and progression of this type of neoplasms has been poorly studied." (PMID 29584702, 2018). "Results revealed that SIRPα was co-expressed with CD68 both in malignant meningioma tissues and mouse subcutaneous xenografts, indicating that the phagocytosis of malignant meningioma cells by macrophages maybe mediate by CD47-SIRPα axis." (PMID 37171006, 2023). "Furthermore, increased expression of CD68 was also selectively observed in tumors of rare subtype of meningiomas, such as the xanthomatous or histiocytic meningioma." (PMID 35205781, 2022). "Furthermore, the increased expression of CD68 can also be selectively observed in tumor cells of rare subtypes of meningiomas, such as the histiocytic or xanthomatous meningioma." (PMID 35453901, 2022). "As an example, we stained the grade III meningioma, J10, for the common macrophage marker, CD68." (PMID 33167358, 2020). "Sometimes, metaplastic meningiomas may show xanthomatous differentiation consisting of CD68 positive tumor cells; in this subtype, groups of macrophagic elements are present." (PMID 29584702, 2018). "Patient-derived meningioma spheroids closely recapitulated morphological and molecular features of matched patient tissues, including patient histology, genomic alterations, and components of the immune microenvironment, such as a CD68 + and CD163 + positive macrophage cell population." (PMID 38102708, 2023). "However, tumor cells of metaplastic or anaplastic features might show xanthomatous characteristics, which consists of CD68+ meningioma cells." (PMID 35453901, 2022). "In a small study exerted by Proctor and colleagues, TAM infiltration was analyzed in a cohort of 30 meningioma samples (n = 16 WHO°1, n = 12 WHO°2 and n = 2 WHO°3) using multicolor IF staining for CD68+ and CD163+ (M2-like macrophage marker)." (PMID 39273576, 2024).
meningioma (continued). "Simultaneously, COX-2 expression has been suggested as a relevant parameter for evaluating meningioma proliferation, and positive correlations have been observed between higher MIB-1 indices and the presence of CD68-positive macrophages." (PMID 37370707, 2023). "The first case is a right-sided frontal convexity meningioma with both an increased MIB-1 index (10%) and diffuse infiltrates of CD68+ macrophages." (PMID 35205781, 2022). "Although we detected some CD68+ cells, the widespread expression of MAOB throughout the tissue suggests that the majority of immunostaining is genuinely derived from meningioma cells themselves." (PMID 33167358, 2020). "This study integrated 16S rRNA sequencing of fecal samples from 15 treatment-naïve WHO grade I meningioma patients (MPs) and 15 healthy controls (HCs) with immunohistochemical profiling of tumor immune infiltrates (MPO+ neutrophils, CD68+ macrophages, CD3+ T cells)." (PMID 42059606, 2026). "Between 2000 and 2020, 128 patients with clinical data, tumor imaging data, inflammatory laboratory (plasma fibrinogen, serum C-reactive protein) data, and neuropathological reports (MIB-1, mitotic count, CD68 staining) underwent surgery for spinal WHO grade 1 and 2 meningioma." (PMID 36091152, 2022). "CD163 is a well-established M2 macrophage marker and has previously been shown using immunohistochemistry to be in high abundance in atypical grade II meningiomas but, unlike previous authors, we correlated CD68 and CD163 expression with NF2 status." (PMID 32070062, 2020). "The histiocytes were positive for CD68, CD163, and ALK, and negative for EMA, PR, and SSTR2, which ruled out the diagnosis of meningioma." (PMID 36915094, 2023). "From a neuropathological lens, correlating emperipolesis with S100 or CD68 co-expression and, when available, negative Langerin remains critical to distinguish IC-RDD from meningioma, inflammatory pseudotumor, and Langerhans-cell lesions in small intracranial samples." (PMID 41351624, 2025). "However, lymphocytes and positive reactions for CD21, CD68 and CD35 are not observed in meningiomas." (PMID 23761812, 2013). "Interestingly, the authors reported higher PD-L1 expression in CD68-negative cells (likely tumor cells) in WHO°2 and °3 tumors and described further high PD-L1+/CD68- staining as an independent prognostic marker for poor overall survival in meningioma patients." (PMID 39273576, 2024).
dementia (23 papers, 2009 to 2025). Loss of intellectual abilities interfering with an individual's social and occupational functions. "Age-associated deep-subcortical white matter lesions (DSCLs) are an independent risk factor for dementia, displaying high levels of CD68+ microglia." (PMID 38674030, 2024). "Using available markers in CFAS, dementia was associated with higher CD68 and lower Iba1 suggesting that dementia is associated with a change in microglial phenotype." (PMID 37462105, 2023). "CD68+ microglia positively associate with dementia, neuritic plaques and tangles in the ageing population." (PMID 31947996, 2020). "The presence of dementia was associated positively with CD68 (P < 0.001), MSR-A (P = 0.010) and CD64 (P = 0.007) and negatively with Iba1 (P < 0.001)." (PMID 27256292, 2016). "The association of CD68 with dementia, poor cognitive function and tau pathology (i.e. neuritic plaques and tangles) is particularly strong." (PMID 27256292, 2016). "In a series of former American football players with neuropathologically confirmed CTE, we found that rs3173615, a coding SNP in TMEM106B that was previously implicated with risk of FLTD-TDP, was associated with p-tau density, CD68 density, synaptic loss, and dementia status in case-only analyses." (PMID 30390709, 2018). "Additionally, TMAO upregulates macrophage scavenger receptors and induces CD68 expression, a cellular marker positively associated with dementia." (PMID 30579367, 2018). "In addition to its association with RHI exposure and ptau pathology, CD68 cell density in the DLF appears to plays an indirect role in the development of dementia in CTE, mediated through ptau pathology." (PMID 27793189, 2016). "In a post mortem study of AD patients, CD68+ expression was strongly related to neuritic plaques and tangles, as well as the dementia score." (PMID 40801621, 2025). "It was previously shown that CD68 protein levels were increased in APOE e4 allele carriers, and it was strongly associated with dementia and poor cognitive functioning." (PMID 40646278, 2025). "Overall, this evidence implies a close relationship between TSPO, CD68-related microglial phagocytosis, tau-related neurodegeneration and dementia." (PMID 39540994, 2024). "For example, Iba1 was negatively associated with AD while levels of CD68, MSR-A, and CD64 expression were positively related to the presence of dementia." (PMID 32082319, 2020). "This suggests that the effect CD68 has on dementia is mediated through the development of tau pathology." (PMID 27793189, 2016). "The protective ε2 allele is associated with high expression of Iba1 (absence of dementia, good cognition), while the risk ε4 allele is associated with CD68, HLA-DR and CD64 (presence of dementia and bad cognition)." (PMID 27256292, 2016). "Overall, in both analyses (dementia and MMSE score), good cognition was associated with higher Iba1 and lower CD68 expression." (PMID 27256292, 2016). "CD68 expression has been associated with dementia and with poorer cognition in subjects with AD and in non-demented subjects." (PMID 39540994, 2024). "CD68 expression was unaffected by diet or dementia in both males and females." (PMID 35568928, 2022). "This study concluded that the presence of dementia correlated positively with CD68 levels but negatively with Iba-1 levels, and that different microglial populations may coexist within the brain." (PMID 30682074, 2019). "Secondly, in relation to the MMSE score, among the participants without dementia, there was a significant positive relationship with Iba1 (P < 0.001) and a negative relationship with CD68 (P = 0.033); no other significant association was observed." (PMID 27256292, 2016). "A binary logistic regression demonstrated dementia was significantly predicted by CD68 independent of age, but that association was eliminated when a measure of ptau pathology was included in the model." (PMID 27793189, 2016).
dementia (continued). "In the participants with dementia and Alzheimer’s pathology, the relationships between CD68, MSR-A and less strongly HLA-DR with tau pathology (i.e. tangles and neuritic plaques) are consistent with either microglial activity promoting or responding to tau accumulation." (PMID 27256292, 2016). "Interestingly, the brains of individuals resilient to dementia despite robust Alzheimer’s neuropathology (amyloid plaques and neurofibrillary tangles) displayed lower numbers of CD68+ microglia in the temporal lobe and higher levels of the cytokines IL-6, IL-1β, IL-1073." (PMID 32917850, 2020). "Cd68 labels lysosomal and endosomal transmembrane glycoprotein of microglia, indicating phagocytic activity, with presence of CD68, MSR-A, and HLA-DR being related to dementia and scores of poor cognitive function in AD." (PMID 36436561, 2022). "We primarily used CD68 as a marker of phagocytic microglia, as well as other markers of microglia including Iba‐1 and TMEM119, and the myeloid cell marker TREM2 to assess dementia‐specific changes." (PMID 35748290, 2022). "We showed the association of Iba1 expression with the absence of dementia and scores of good cognition, whereas the presence of CD68, MSR-A and HLA-DR is related to dementia and scores of poor cognitive function." (PMID 27256292, 2016). "To better solidify our findings in the monkey model, we investigated whether Ki-67+ cells were also positive for CD68 in subjects diagnosed with HIVE, the pathological correlate of HIV dementia." (PMID 27610547, 2016). "Thus, high loads of CD68, MSR-A and CD64 and a low Iba1 expression were related to the presence of dementia." (PMID 27256292, 2016). "A binary logistic regression demonstrated that a diagnosis of dementia was significantly predicted by CD68 cell density (OR = 1.010, p = 0.011) independent of age (OR = 1.055, p = 0.007), but this effect disappeared when ptau pathology was included in the model." (PMID 27793189, 2016). "Interestingly, when ptau pathology was included into the model, NFT density (OR = 1.12, p = 0.007) significantly predicted dementia independent of age (OR = 1.050, p =0.039), but CD68 density (OR = 1.007, p = 0.079) was no longer a significant predictor." (PMID 27793189, 2016). "Inversely, the same study showed that in people without dementia, cognitive function was positively correlated with IBA-1 but negatively with CD68." (PMID 37457817, 2023). "While previous studies investigating microglial CD68 expression in the ALS hippocampus did not compare to control cases, it has been noted that hippocampal CD68 expression did not correlate with pTDP-43 load, dementia state, or impaired executive function." (PMID 37118836, 2023). "We have employed linear models to assess the regional influence within patients with and without dementia, which treats patient ID as a random effect and region as a fixed effect and these were fitted into the log (CD8), log(CD68), log (P24) transformation data." (PMID 19951441, 2009). "However, based on cellular infiltration of CD68+ and CD8+ cells alone (not taking HIV into account), we could not distinguish between patients with and without dementia." (PMID 19951441, 2009).
renal fibrosis (23 papers, 2013 to 2025). A final common manifestation of a wide variety of chronic kidney diseases characterized by glomerulosclerosis and tubulointerstitial fibrosis. "Anti-inflammation (downregulation of CX3CL1, reduction in CD68+ macrophages infiltration) and decreased renal fibrosis (reduction of α-SMA).Downregulated CX3CL1 was associated with specific miRNAs in EVs (miR-15a, miR-15b, mi-R16)." (PMID 35359949, 2022). "Impressively, the presence of kidney IGF1/CD68+ macrophage infiltration and the relevance of renal IGF1/CD68 expression to the degree of renal fibrosis were confirmed in human CKD." (PMID 39119903, 2024). "As one of the important markers of macrophages, CD68 expression was significantly increased in the kidneys of UUO-induced renal fibrosis model mice." (PMID 36357407, 2022). "Biopsy tissues from renal fibrosis patients showed that only in acute and active renal fibrosis does the number of CD68+α-SMA+ MMT cells correlate with the total α-SMA+ myofibroblast population." (PMID 35990655, 2022). "Additionally, CD-68 levels have been associated with the progression of CKD and renal fibrosis via glomerular disease." (PMID 37373209, 2023). "CD68+ macrophages contribute to renal inflammation, which initiates renal fibrosis." (PMID 29425253, 2018). "A significant macrophage infiltrate was also evident on day 28 AA in WT mice as shown by increased CD68 mRNA levels, with a dramatic increase in the expression of CD206 —a marker of alternatively activated macrophages that has been implicated in promoting renal fibrosis." (PMID 34678993, 2021). "Considering the co-expression of CD68 and α-SMA may contribute to the macrophage-to-myofibroblast transition, especially during renal fibrosis, it may partially support the explanation that the more severe lesions in the gadodiamide group were because of the high expression of CD68 and α-SMA." (PMID 34705860, 2021). "To validate the results obtained from the mouse CAR model, we applied clinical biopsy specimens from patients with CAR to assess the presence of MMT cells (co‐expressing CD68 and α‐SMA) and the METTL3 expression across different extents of renal fibrosis." (PMID 39869489, 2025). "In this study, the quantity of CD68+ macrophages and α-SMA was employed as a means of gauging the extent of renal fibrosis." (PMID 39830341, 2024). "Q-PCR indicated a significant reduction in the expression of renal fibrosis-related genes (fn-1, αSMA, Col1a1, Col3a1, Ctgf, fsp1, KIM) and inflammatory cytokines (Tgfα, Tgfβ, Il-1b, Il-4, Il-6, CD44, CD68) in the kidney of the acetate-treatment group." (PMID 36922584, 2023). "In a direct way, a part of BMDMs transition into myofibroblasts, which coexpress CD68 and α-SMA through MMT and produce collagen I to contribute to renal fibrosis." (PMID 35990655, 2022). "To determine whether macrophages are involved in UUO-induced renal fibrosis in the contralateral kidney of UUO rats, we performed immunofluorescent co-staining using specific antibodies against monocyte/macrophage marker CD68 and myofibroblast marker α-SMA." (PMID 33716747, 2021). "Real‐time PCR analysis found elevated levels of mRNA for markers of renal inflammation (CD68, TNF‐α, CCL2) and renal fibrosis (TGF‐β1, fibronectin, collagens I and IV) in diabetic compared to nondiabetic kidneys, which were not different in male and female mice." (PMID 31535473, 2019). "Furthermore, the majority of CD68+α-SMA+ cells expressed CD206, suggesting that it is predominantly M2-type macrophages that undergo MMT in human renal fibrosis." (PMID 27906172, 2016). "Day 28 AA CypD-/- mice were not protected from renal fibrosis, with no appreciable difference compared to day 28 AA WT mice in terms of collagen IV deposition, increased mRNA levels for collagen I, α-SMA, CD68 or CD206, or the loss of CD31+ peritubular capillaries." (PMID 34678993, 2021).